SIX2 (SIX homeobox 2)
Description:
Transcription factor that plays an important role in the development of several organs, including kidney, skull and stomach. During kidney development, maintains cap mesenchyme multipotent nephron progenitor cells in an undifferentiated state by opposing the inductive signals emanating from the ureteric bud and cooperates with WNT9B to promote renewing progenitor cells proliferation. Acts through its interaction with TCF7L2 and OSR1 in a canonical Wnt signaling independent manner preventing transcription of differentiation genes in cap mesenchyme such as WNT4. Also acts independently of OSR1 to activate expression of many cap mesenchyme genes, including itself, GDNF and OSR1. During craniofacial development plays a role in growth and elongation of the cranial base through regulation of chondrocyte differentiation. During stomach organogenesis, controls pyloric sphincter formation and mucosal growth through regulation of a gene network including NKX2-5, BMPR1B, BMP4, SOX9 and GREM1. During branchial arch development, acts to mediate HOXA2 control over the insulin-like growth factor pathway. May also be involved in limb tendon and ligament development (By similarity). Plays a role in cell proliferation and migration.
Tractability: PROTAC: ubiquitination databases record sites on it.
Gene: Protein-coding gene on chromosome 2 (45,005,182 to 45,009,452, reverse strand). Ensembl gene ENSG00000170577.
Subcellular location: Nucleus
Subcellular location (Human Protein Atlas): Nucleoplasm; Nuclear membrane
Pathways (Reactome):
Developmental Biology: Formation of the ureteric bud
Gene Ontology:
Molecular function: protein binding; sequence-specific double-stranded DNA binding; DNA-binding transcription factor activity; DNA-binding transcription factor activity, RNA polymerase II-specific; RNA polymerase II cis-regulatory region sequence-specific DNA binding; DNA binding; DNA-binding transcription activator activity, RNA polymerase II-specific; protein-containing complex binding; sequence-specific DNA binding
Biological process: cell migration; cell population proliferation; kidney development; anatomical structure morphogenesis; anterior/posterior axis specification; embryonic digestive tract morphogenesis; mesenchymal cell differentiation involved in kidney development; mesenchymal stem cell maintenance involved in nephron morphogenesis; mesenchymal stem cell proliferation; mesenchymal to epithelial transition involved in metanephros morphogenesis; mesodermal cell fate specification; nephron development; nephron morphogenesis; positive regulation of chondrocyte proliferation; regulation of branching involved in ureteric bud morphogenesis; regulation of transcription by RNA polymerase II; positive regulation of transcription by RNA polymerase II; regulation of chondrocyte differentiation; regulation of DNA-templated transcription; regulation of ossification
Cellular component: nucleoplasm; chromatin; nucleus; transcription regulator complex
Genetic constraint (gnomAD): Loss-of-function variants: 20 observed, 23.43 expected, observed/expected ratio (o/e) 0.85, 90% interval 0.6 to 1.24. The upper end of that interval is the gene's LOEUF score, 1.24, which puts it in group 5 of 6, group 1 being the genes least tolerant of losing a copy. Missense variants: 360 observed, 419.78 expected, observed/expected ratio (o/e) 0.86, 90% interval 0.79 to 0.94. Synonymous variants: 195 observed, 191.65 expected, observed/expected ratio (o/e) 1.02, 90% interval 0.9 to 1.15.
Homologues: Orthologues: chimpanzee SIX2 (100% identical), macaque SIX2 (99% identical), pig SIX2 (99% identical), dog SIX2 (99% identical), guinea pig SIX2 (99% identical), mouse Six2 (99% identical), rat Six2 (99% identical), rabbit SIX2 (98% identical), tropical clawed frog six2 (90% identical), zebrafish six2a (88% identical), Drosophila melanogaster Optix (44% identical), Caenorhabditis elegans ceh-32 (41% identical). Paralogues in human: SIX1 (76% identical), SIX4 (51% identical), SIX5 (47% identical), SIX3 (46% identical), SIX6 (45% identical), ANHX (24% identical).
Diseases named in the same sentence as SIX2 in open-access papers:
SIX2 is named in the same sentence as 49 diseases in open-access papers, as found by Europe PMC text mining. Sharing a sentence is not in itself a finding about the gene and the disease. The quoted sentences say what the papers report.
breast carcinoma (13 papers, 2015 to 2023). "Intriguingly, a more recent study of Six2 in breast cancer found that Six2 expression is associated with greater metastatic potential owing to both its induction of ZEB2 expression and its repression of E-cadherin transcription through promoter methylation." (PMID 32829692, 2020). "All six of the SIX family members have been implicated in breast cancer and SIX2 is upregulated in basal-like breast cancer." (PMID 30914750, 2019). "Recent studies have reported that SIX2, a developmental transcription factor, promotes breast cancer metastasis via the epithelial-mesenchymal transition (EMT) pathway or the induction of the cancer stem cell program." (PMID 36739462, 2023). "Recently, SIX2 was reported to promote cancer metastasis in breast cancer and to attenuate chemotherapeutic sensitivity in non-small cell lung cancer by transcriptional and epigenetics regulation of E-cadherin." (PMID 32631391, 2020). "The homeobox protein Six2 has been shown to promote the stemness of breast cancer cells and play a role in kidney development, but its involvement in RCC progression has not previously been investigated." (PMID 31420918, 2019). "Increased SIX1–3 expression is linked to high histological grade and ER status, and that SIX2 and SIX3 are upregulated in basal-like breast cancer." (PMID 27399099, 2016). "Our analysis indicated that SIX1, SIX2, and SIX4 were associated with clinical prognosis of whole breast cancer population at mRNA level." (PMID 27399099, 2016). "Furthermore, SIX2 was statistically associated with RFS (HR: 1.22, 95% CI: 1.02–1.45; P = 0.327 and I2 = 12.9%) and MFS (HR: 1.24, 95% CI: 1.00–1.53; P = 0.478 and I2 = 0.0%), but not correlated with OS (HR: 1.08, 95% CI: 0.86–1.36; P = 0.748 and I2 = 0.0%) of whole breast cancer population." (PMID 27399099, 2016). "Likewise, many were upregulated by recurrent downstream fusions (geneDIB), including SIX2 in thyroid and CHI3L1 and OR1D4 in breast cancers." (PMID 32631391, 2020). "Sineoculis homeobox homolog (SIX) family proteins, including SIX1, SIX2, SIX3, SIX4, SIX5, and SIX6, have been implicated in the initiation and progression of breast cancer, but the role of each member in breast tumor is not fully understood." (PMID 27399099, 2016). "SIX1, SIX2, and SIX4 are activated in breast cancer patients." (PMID 27399099, 2016). "Moreover, SIX genes are deregulated in several types of malignancies, including breast cancer and hepatocellular carcinoma (SIX1), lung cancer (SIX2), chondrosarcoma (SIX3), and acute T-cell leukemia (SIX6)." (PMID 26473286, 2015).
Wilms tumor (11 papers, 2018 to 2025). An embryonal neoplasm characterized by the presence of epithelial, mesenchymal, and blastema components. "The same Q177R mutation has been identified in SIX2 in Wilms tumors but occurs almost half as frequently as SIX1-Q177R." (PMID 37815464, 2023). "Consistent with this view, human mutations in SIX2 are associated with renal hypodysplasia and the malignant transformation of progenitor cells in Wilms’ tumor, a pediatric nephroblastoma." (PMID 29377931, 2018). "HSF4 could be used as a prognostic marker in CRC, while SIX2 might be a diagnostic and prognostic biomarker in Wilms’ tumor." (PMID 34178996, 2021). "GSEA showed that the upregulated genes in ENL-mutant Wilms tumors were positively enriched, and downregulated genes in tumors were negatively enriched, in Six2-ENLT mutant mouse kidneys, indicating potential clinical relevance of our mutant mouse models." (PMID 40087269, 2025). "SIX2 is elevated in Wilms Tumor and the mean log2 counts for our normal tissue and cell lines were 2.54 (standard deviation of 0.32) whereas in our FHWT was 3.73 (standard deviation of 0.20)." (PMID 38589567, 2024). "SIX2 is expressed in the immature blastema of the developing kidney and is found to be expressed in Wilms tumour blastema." (PMID 37186071, 2023). "SIX2 is expressed in the metanephric mesenchyme of the human foetal kidney and it is usually found to be expressed in Wilms tumour blastema." (PMID 37186071, 2023). "If RA induces differentiation of Wilms tumour cells, in theory, decreased SIX2 expression should be noted in RA treated cells." (PMID 37186071, 2023). "SIX2 overexpression has been identified in the pediatric cancer Wilms tumor as well as in renal cell carcinoma and nephroblastoma." (PMID 34490256, 2021). "Cluster 2 showed expression of the nephron progenitor markers SIX1, SIX2 and CITED1, as well as the stromal marker PAX3 that has previously been associated with myogenic Wilms' tumours." (PMID 30846463, 2019). "Furthermore, upregulated DEGs identified in ENL-mutant Wilms tumors are overall positively enriched in the Six2-ENLT and Foxd1-ENLT1 mutant kidneys, highlighting the clinical relevance of our mouse models." (PMID 40087269, 2025). "SIX2 is commonly expressed in Wilms tumour blastema and it could be expected that SIX2 was expressed in CCG99‐11 cells, but it was not in the cell cultures of the present study." (PMID 37186071, 2023). "SIX2 is recurrently mutated in Wilms tumour, but mutations in the gene do not seem to affect SIX2 protein expression according to the literature." (PMID 37186071, 2023). "Six2 overexpression in Wilms tumor cells resulted in downregulation of Wnt pathway genes." (PMID 34490256, 2021). "It was shown that tubuloids derived from the healthy kidney tissue of Wilms tumor patients were negative for SIX2 expression, while the tumoroids from the same patients showed high SIX2 expression." (PMID 33672414, 2021).
colorectal cancer (7 papers, 2019 to 2022). A primary or metastatic malignant neoplasm that affects the colon or rectum. "The YAP1/SIX2 axis is responsible for DDX3X-induced cell invasiveness in colorectal cancer harbouring wild-type KRAS." (PMID 33627125, 2021). "SIX2 also was reported to play a critical role in invasion and drug resistance in colorectal cancer." (PMID 32631391, 2020). "In colorectal cancer, DDX3X expression has been detected, and positive associations between DDX3 and KRAS, YAP1, and SIX2 have been observed in KRAS wild-type patients." (PMID 31906196, 2019). "More importantly, we identified genes (e.g., Trim63, Fos, Col1a1, and Six2) that were regulated by high-intensity aerobic exercise, which adversely affected colorectal cancer development, and confirmed their effects in vitro using knockdown and overexpression systems." (PMID 35801156, 2022). "In addition to promoting metastasis, the DDX3X-induced YAP1/SIX2 axis might be responsible for resistance to treatment with the anti-EGFR antibody cetuximab (CTX) in colorectal cancer harbouring wild-type KRAS via enhanced autophagy and anti-apoptotic mechanisms." (PMID 33627125, 2021). "SIX2 has been detected in other cancers such as hepatocellular carcinoma (HCC), non-small cell lung cancer and colorectal cancer." (PMID 34490256, 2021). "Moreover, the YAP1/six2 axis is required for DDX3-mediated tumor aggressiveness and cetuximab resistance in KRAS wild-type colorectal cancer." (PMID 30832689, 2019).
frontonasal dysplasia (4 papers, 2012 to 2024). A group of rare bone development disorders characterized by an array of abnormalities affecting the eyes, forehead, and nose, and linked to midfacial dysraphia. "Loss of human SIX2 is associated with frontonasal dysplasia, while mice harboring a similar locus deletion exhibit a nasal cleft." (PMID 38063857, 2024). "Brachyrrhine (3H1 Br/+) mice display frontonasal dysplasia, thought to be caused by loss of the developmentally important transcription factor Six2, although in this case associated with reduced proliferation in the craniofacial region, rather than increased cell death." (PMID 22629443, 2012). "With these insights into regulation of Six2, our attention was drawn to the Brachyrrhine (Br) mouse, an X-irradiation induced mutant that displays kidney hypoplasia and frontonasal dysplasia, and maps to the Six2 region of chromosome 17." (PMID 29377931, 2018). "While SIX2 missense variants have been associated with renal hypodysplasia, SIX2 haploinsufficiency has not been linked to a renal phenotype so far but to frontonasal dysplasia, ptosis, and hearing loss." (PMID 34122504, 2021).
non-small cell lung carcinoma (3 papers, 2020 to 2023). A group of at least three distinct histological types of lung cancer, including non-small cell squamous cell carcinoma, adenocarcinoma, and large cell carcinoma. "Six2 promotes non-small cell lung cancer cell stemness via transcriptionally and epigenetically regulating E-cadherin." (PMID 37792303, 2023).
renal agenesis (3 papers, 2012 to 2022). Renal agenesis (RA) is a form of renal tract malformation characterized by the complete absence of development of one or both kidneys (unilateral RA or bilateral RA respectively), accompanied by absent ureter(s). "Systemic deletion of nephronectin in mice (Npnt–/–) results in renal agenesis whereas conditional deletion of nephronectin in nephron progenitor cells in mice (Npntf/f; Six2-Cre) leads to mesangial sclerosis." (PMID 33553140, 2020). "These phenotypes were striking and differed from the previously reported Six2-Cre;β-catenin gain of function phenotype, which is renal agenesis at birth." (PMID 22792366, 2012). "Mice lacking the Eya1 exhibit renal agenesis due to lack of MM formation, while Eya1 deletion after UB outgrowth results in downregulation of Six2 expression and depletion and premature differentiation of the NPCs." (PMID 36130284, 2022).
renal hypoplasia (3 papers, 2014 to 2023). Renal hypoplasia is a developmental anomaly in which one or both kidneys (unilateral or bilateral renal hypoplasia, respectively) have a deficit in the number of nephrons and may be small. "Obligate expression of GLI3R (Six2Cre;Rosa26Gli3TFLAG/+) targeted to the Six2+ nephrogenic lineage inhibits nephrogenesis via inhibition of Six2+ progenitor cell self-renewal resulting in renal hypoplasia." (PMID 37675356, 2023). "Studies into cases of ‘non-syndromic’ renal hypoplasia have identified mutations in several key genes which include PAX2, SIX2, BNP4, SALL1, UMOD and TCF2." (PMID 24886545, 2014). "Also the inactivation of Six2 gene results in premature differentiation of mesenchymal cells into epithelia and depletion of this progenitor cell population leads to severe renal hypoplasia." (PMID 27582005, 2016).
BOR syndrome (2 papers, 2014 to 2024). "The SIX2 gene is a family of SIX genes associated with the BOR syndrome, including external ear abnormalities and other congenital malformations." (PMID 38594752, 2024). "Indeed, mutations in Six gene family members such as SIX1 and SIX5 also cause BOR syndrome while mutations in SIX2 have been reported in patients with renal hypodysplasia, a phenotype observed in patients with BOR syndrome." (PMID 24489909, 2014).
colon cancer (2 papers, 2021). "In the GCSC database, the methylation levels of FGF8, NOG, TCF15, TWIST1, TBX5, SIX2, and TIAM1 are higher in colon cancer." (PMID 34526059, 2021). "Except for the heterozygous deletion of TWIST1 and SNAI1 in CRC, and the lack of SIX2 in colon cancer, all other genes have heterozygous deletions." (PMID 34526059, 2021).
prostate carcinoma (2 papers, 2024). A carcinoma that arises from epithelial cells of the prostate gland. "Depletion of SIX2 in androgen-independent PC-3 prostate cancer cells induced a switch from a stem-like to an epithelial state, resulting in reduced cancer-related properties such as proliferation, colony formation, and metastasis both in vitro and in vivo." (PMID 38554106, 2024). "Collectively, our findings provide compelling evidence that the depletion of SIX2 may represent a promising strategy for overcoming the cell plasticity mechanisms driving antiandrogen resistance in prostate cancer." (PMID 38554106, 2024).
renal fibrosis (2 papers, 2017 to 2023). A final common manifestation of a wide variety of chronic kidney diseases characterized by glomerulosclerosis and tubulointerstitial fibrosis. "In our previous study, we found that metanephric mesenchyme-specific Zeb2-cKO (Zeb2fl/fl;Six2-Cre+) mice develop glomerulocystic disease without renal fibrosis." (PMID 36445780, 2023). "The hypomethylation of certain genes, especially key renal transcription factors (Hepatocyte nuclear factor, HNF; Transcription factor AP, TCFAP; Sine oculis homeobox homolog 2, SIX2), has been shown to enhance the baseline expression levels of TGF-β, which participates in renal fibrosis." (PMID 28969091, 2017).
Saethre-Chotzen syndrome (2 papers, 2021 to 2023). Saethre-Chotzen syndrome (SCS) is an inherited craniosynostosis syndrome characterized by unilateral or bilateral coronal synostosis, facial asymmetry, ptosis, strabismus and small ears with prominent crus, among other less common manifestations. "Correspondingly, in Twist1+/−; Tcf12+/− mutants, a robust model for Saethre-Chotzen Syndrome coronal synostosis, Erg+/Six2+ progenitors were reduced as early as E14.5 yet ectocranial populations were relatively unaffected." (PMID 34376651, 2021). "Additionally, Six2+ SMSCs were reduced in the coronal suture of E14.5 and E15.5 embryos from a mouse model of Saethre-Chotzen syndrome (Twist+/−; Tcf12+/−) with coronal synostosis, suggesting the potential functions of Six2+ SMSCs in suture patency." (PMID 37325554, 2023). "Lineage tracing reveals an embryonic Six2+ osteoprogenitor population that contributes to the postnatal suture mesenchyme, with these progenitors being preferentially affected in a Twist1+/−; Tcf12+/− mouse model of Saethre-Chotzen Syndrome." (PMID 34376651, 2021).
branchio-oto-renal syndrome (1 paper, 2022). "Both genes are expressed in nephron progenitors of human fetal kidneys, and mutations in SIX1 or SIX2 cause branchio-oto-renal syndrome or renal hypodysplasia respectively." (PMID 35178390, 2022).
cardiomyopathy (1 paper, 2015). A disease of the heart muscle or myocardium proper. "This shows that interruption of the EYA4 interaction with SIX1 and SIX2 impairs cardiac function, resulting in cardiomyopathy." (PMID 25781927, 2015).
craniosynostosis (1 paper, 2021). Craniosynostosis is defined as the premature fusion of one or more cranial sutures leading to secondary distortion of skull shape resulting in skull deformities with a variable presentation. "We show that asymmetric distribution of Erg and Six2 is lost in Twist1+/−;Tcf12+/− mutants, and in a companion study that similar asymmetric distribution of Grem1+ progenitors is lost in Tcf12−/− mutants, consistent with bones meeting end-on-end and fusing in these craniosynostosis models." (PMID 34376651, 2021).
diabetes (1 paper, 2021). "Nucleotide variants in the locus encoding SIX2 and SIX3 have been linked by GWAS to increased risk for type 2 diabetes (T2D) and diabetes-related traits." (PMID 33893274, 2021).
fibrosis (1 paper, 2022). the formation of excess fibrous connective tissue in an organ or tissue in a reparative or reactive process. "While the promoter of the Nsf (nephrogenic system fibrosis) gene was co-occupied by Eya1/Six2, Six2 alone also bound to a distal intronic CRE/enhancer ∼+70-kb, and Eya1 alone occupied another distal intronic CRE ∼+35-kb without H3k27ac-deposition but with two REST motifs." (PMID 36130284, 2022).
gastric cancer (1 paper, 2025). A primary or metastatic malignant neoplasm involving the stomach. "to be transcriptionally activated by SIX2, thereby promoting stemness and progression in gastric cancer." (PMID 41395115, 2025).